IL15 (interleukin 15)
Diseases named in the same sentence as IL15 in open-access papers (continued):
Sharing a sentence is not in itself a finding about the gene and the disease.
cancer (continued). "The ability of IL-15 to promote both NK cell and CD8 T cell responses has led to interest in IL-15 as a cancer immunotherapy." (PMID 25879689, 2015). "Another cytokine that helps NK cell activation is IL15, and it is currently being tested clinically in various types of cancer." (PMID 26284063, 2015). "As TNF-α and IFN-γ induce muscle wasting under cancer cachexia and IL-15 was shown to prevent it, we first examined genes that regulate muscle mass." (PMID 26417430, 2015). "The gamma common cytokine IL-15 is currently undergoing clinical trials for the treatment of malignancies, due to its well-established role in the regulation of natural killer and CD8+ T cell immune responses." (PMID 26500048, 2015). "How to best incorporate IL-15 into vaccine formulations for superior cancer immunotherapy remains a challenge." (PMID 25941586, 2014). "IL15 is a pro-inflammatory cytokine with significant potential for stimulating T lymphocytes and NK cells against cancer." (PMID 25329832, 2014). "Prior to testing the therapeutic capacity of the recombinant IL15Rα-IL15 virus (vMyx-IL15Rα-tdTr), we tested its capacity to infect relevant murine cancer cell lines in vitro." (PMID 25329832, 2014). "If effective and safe, this approach would provide a more practical administration approach for IL-15 and the potential for expanded clinical trials to combine with monoclonal antibodies or NK cell infusions for a variety of malignancies." (PMID 25054077, 2014). "IL-15 gene therapy and rIL-15 are being used to generate ex vivo DC vaccines for cancer immunotherapy in preclinical models and clinical trials/studies." (PMID 25941586, 2014). "IL15 has been proposed as a useful cytokine for immunotherapy for cancer, and the complexing of IL15 with its receptor alpha component has been shown to enhance its biological activity." (PMID 25329832, 2014). "Interleukin-15 (IL-15) is an immunostimulatory cytokine that has received attention recently as a promising cancer immunotherapeutic agent." (PMID 24312353, 2013). "In this context, IL-15 has been suggested to be a substitute for IL-2 as a vaccine adjuvant in the prevention of cancer and infectious diseases." (PMID 24391824, 2013). "Multiple clinical trials evaluating systemically administered IL-15 as a therapeutic agent for treatment of cancers of varying origins are underway." (PMID 24312353, 2013). "Our findings thus establish a previously unrecognized ‘killer DC’ function for IL-15 DCs, providing further support to their application in DC-based cancer immunotherapy protocols." (PMID 23284789, 2012). "IL-2, IL-7, IL-15 and IL-21, sharing a common receptor γ chain (c-γ), control T lymphocyte homeostasis and proliferation and play major roles in regulating cancer-immune system interactions." (PMID 21943235, 2011). "Recent years have seen a number of cytokines, including GM-CSF, IL-7, IL-12, IL-15, IL-18 and IL-21, enter clinical trials for patients with advanced cancer." (PMID 24213115, 2011). "IL-15 has demonstrated significant therapeutic activity in several pre-clinical murine models of cancer." (PMID 24213115, 2011). "Since fully mature, immunostimulatory DCs are required for successful cancer immunotherapy, the clinical use of cytokine cocktail-matured IL-15 DCs cannot be recommended." (PMID 20021667, 2009). "Using IL15 for cancer immunotherapy based on NK cell activity and immunoglobulin production had been demonstrated previously." (PMID 19422685, 2009). "In order to use IL15 for cancer treatment and to avoid treating IL15 many times, gene therapy is considered." (PMID 19422685, 2009). "This review summarizes recent progress in IL-15-based cancer immunotherapy, integrates emerging insights into IL-2Rβγ-driven CD8+ T-cell fate decisions, and discusses key opportunities and challenges for translating IL-15-mediated immune enhancement into durable clinical benefit." (PMID 42039157, 2026).
cancer (continued). "IL-15 in cancer cachexia may have a dual role as a biomarker for muscle mass and as a potential preclinical drug candidate." (PMID 40869331, 2025). "An NCI review listed IL‐15 as the most promising candidate among 12 immunotherapy drugs that could potentially cure cancer." (PMID 40799128, 2025). "This may be an augmentation effect caused by the use of IL15, one of the most promising cytokines to activate and expand CD8+ T and NK cells for cancer immunotherapy." (PMID 40886193, 2025). "However, IL15 supplementary therapy encounters challenges such as systemic inflammation and non‐specific stimulation of cancer cells." (PMID 39625860, 2025). "In addition to muscle health, IL-15 plays a role in regulating immune responses and is particularly relevant in pathological conditions such as cancer and autoimmune diseases." (PMID 40869331, 2025). "This analysis showed that cancer monocultures were unaffected by IL-15 concentration." (PMID 40032842, 2025). "Notably, these cells were distinct from NK cells and were dependent on IL-15 derived from cancer cells." (PMID 39877637, 2025). "The optimal method for pediatric cancer patients requires testing and alternative cytokines, such as IL-15, may be more effective than IL-2." (PMID 39310750, 2024). "Li and Silvestre demonstrated that the fourth- generation CD19-targeted CAR (CAR.19) co-expressing IL-15 or IL-15/IL-15Rα significantly enhanced NK-92 cell proliferation, proinflammatory cytokine secretion, and cytotoxic activity against cancer cell lines in vitro and in a xenograft mouse model." (PMID 38245520, 2024). "Nonetheless, although IL-15 armored CAR-NK cells exhibit better anti-cancer activity, IL-15 secreted by these cells may induce severe systemic toxicities, underscoring the need for providing more specific cytokine signals to avoid their systemic toxicities." (PMID 40007761, 2024). "Besides, a study found that the level of miR-27b-3p was reduced significantly while IL-15 expression was elevated in muscle tissue from cancer cachexia patients, and miR-27b-3p was proven to target the IL-15 gene." (PMID 39404384, 2024). "If causal, exercise may influence disease recurrence or progression in cancer survivors, partly through IL‐15‐mediated reductions in adiposity." (PMID 38887915, 2024). "Moreover, TriKE armoring anti-CD16, anti-CD19, and IL-15 enhanced cancer cell lysis and cytotoxicity against CD19-positive tumors." (PMID 38726000, 2024). "A multi‐functional NKCE, PD‐L1/CD16a/IL‐15, was engineered to target PD‐L1‐positive cancer cells." (PMID 39472273, 2024). "If causal, metformin may influence disease recurrence or progression in cancer survivors, partly through IL‐15‐mediated immune upregulation." (PMID 38887915, 2024). "As cancer cell-intrinsic IL-15 promotes cell migration and invasion, we examined whether IL-15 is involved in the process of EMT." (PMID 38637902, 2024). "We therefore examined whether cancer cell-intrinsic IL-15 affects cell migration and invasion in vitro." (PMID 38637902, 2024). "Interestingly, in contrast to cancer cell-intrinsic IL-15, exogenous IL-15 inhibited cell migration in a dose-dependent manner." (PMID 38637902, 2024). "IL-15 plays a pivotal role in the immune response against cancer." (PMID 38672104, 2024). "Moreover, a superactive form of IL-15 (N803) was just recently licensed by the FDA to treat certain cancers." (PMID 39081326, 2024). "One possible adverse effect of using IL-15 with checkpoint inhibitors in cancer immunotherapy is that autoreactive T cells may become active again." (PMID 39507777, 2024). "Similarly, piggyBac transposon which co-expressed with IL-15 was used to generate CAR-NK cells targeting the NKG2D ligand of cancer cells." (PMID 38726000, 2024). "Furthermore, there is satisfactory evidence that interleukins such as IL-15 and IL-23 perform immune modulation and affect many other cancer-suppressing mechanisms." (PMID 39105978, 2024).
cancer (continued). "Thus, our studies imply that endogenous IL-15 in cancer cells plays a pivotal role in the progression of cancer and is an indicator of the responsiveness of tumors to ICB therapy." (PMID 38637902, 2024). "Interleukins, such as IL-2, IL-12, IL-15, IL-18, and IL-21, glucocorticoids, such as cortisone acetate and hydrocortisone, and ascorbic acid can promote the ex vivo proliferation of NK cells in healthy people or cancer patients." (PMID 39286242, 2024). "Neutralizing extracellular IL-15 did not change the migration of Lv-hIL-15 cells compared to that of their counterparts, suggesting that intracellular IL-15 but not extracellular IL-15 contributes to the promotive effect of cancer cell-intrinsic IL-15 on cell migration." (PMID 38637902, 2024). "Notably, the majority of these trials were initiated prior to 2015, with the exception of one (NCT03127098), which began in 2017 and combines a cancer vaccine with the cytokine IL-15." (PMID 38403820, 2024). "IL-2, IL-12, IL-15, IL-18, and IL-21 could promote NK cells entry into S and G2/M phases of the cell cycle in cancer patients or healthy subjects, and thus have been used to induce ex vivo NK cell proliferation." (PMID 39286242, 2024). "Therefore, IL-15 derivatives have garnered attention as potential immunotherapeutic agents for cancer." (PMID 37251333, 2023). "In cancer therapy, repeated doses of IL-7 administration was shown to increase numbers of circulating T cells in a dose-dependent manner, while the different IL-15 therapies increased proliferation and function of circulating NK and CD8+ T cells." (PMID 37767312, 2023). "Interleukin-15 (IL-15) is a promising immunocytokine for cancer therapy." (PMID 37371081, 2023). "Both sides of IL-15 function can be exploited in therapeutic approaches against cancer." (PMID 37153603, 2023). "Thereinto, cytokines like IL-7 and IL-15 were listed among the top twelve immunotherapeutic agents with wide appeal to the immunotherapy and, by consensus, held particular promise for use in cancer therapy, as shown by the US National Cancer Institute in 2008." (PMID 38049832, 2023). "In addition to using IL-15 and its agonists alone in cancer immunotherapy, IL-15 has been incorporated into many cancer-specific pericyte therapies, particularly in combination with chimeric antigen receptor (CAR) engineering." (PMID 37251333, 2023). "In many studies, IL-15 agonists improved cancer degradation compared to wild-type IL-15." (PMID 37046608, 2023). "This suggests that IL-15 is an attractive candidate for cancer immunotherapy." (PMID 36936961, 2023). "In conclusion, IL-15 provides an exciting opportunity to enhance cancer immunotherapy." (PMID 37251333, 2023). "In general, the biomimetic nanovaccine-mediated multivalent IL-15 self-transpresentation (MIST) could trigger T cell-mediated cancer cell destruction in blood circulation to suppress systemic development." (PMID 37875481, 2023). "However, even though IL-15 immunotherapy was shown to strongly increase the number of NK cells in malignancies, a mono-therapy with IL-15 was so far proven ineffective, probably due to counter acting immune-regulatory responses." (PMID 37691935, 2023). "The immunostimulant effect of IL-15 found application in cancer treatment therapies." (PMID 37046608, 2023). "Recombinant human(rh)IL-15, with rhIL-12 and rhIL-18 may prime blood NK cells to differentiate into memory-like NK cells and potentiate their responses against cancer." (PMID 36936961, 2023). "In the cancer context, CD158b upregulation has been negatively associated with NK cell activation and production of CD107, IFN-γ, and perforin even when tumors are exposed to exogenous IL-2 and IL-15 cytokines." (PMID 37949944, 2023). "In addition, the N803 induction of Th1 responses and IFNγ production in the absence of Treg expansion attribute this first-in-class heterodimeric IL-15 agonist with unique promise as a cancer therapeutic." (PMID 37371081, 2023).
cancer (continued). "A clinical trial also revealed that IL-15 infusion in cancer patients could significantly expand NK and memory CD8+ T cell populations." (PMID 37638058, 2023). "Currently, several clinical trials examining the combination of recombinant human IL-15 or IL-15 agonists with nivolumab and/or ipilimumab are ongoing in multiple types of advanced or refractory cancers (NCT02523469, NCT03228667, NCT03520686, and NCT033886320)." (PMID 37409128, 2023). "However, the TME's primary cytotoxic γδ T cell promoters, IL-2 and IL-15, are crucial for regulating cytotoxic γδ T cells in cancer immunotherapy." (PMID 37841886, 2023). "One of the most promising targets for cancer immunotherapy is IL-15." (PMID 37251333, 2023). "Several clinical cancer trials have tested the safety and effect of IL-15 therapies." (PMID 37767312, 2023). "Due to its powerful effects on cytolytic NK and T cells without causing the expansion of suppressive Treg cells, IL-15 has recently emerged as an alternative to IL-2 in cancer therapy." (PMID 37483629, 2023). "As one of the most common γ-chain cytokines, IL15 has great potential as an cancer immunotherapy." (PMID 38054018, 2023). "In addition to using IL-15 and its derivatives alone in cancer immunotherapy, IL-15 has also been incorporated into many adoptive cell therapies against cancer, specifically in combination with chimeric antigen receptor (CAR) engineering." (PMID 38001643, 2023). "For example, upregulation of IL-15 improves cancer-testis antigens (CTA) invasion." (PMID 37251333, 2023). "However, recent investigation indicated the benefit of targeted gene transfer approaches in providing a higher local dosage of IL-15 in order to result in more effective cancer immunotherapy." (PMID 36742134, 2023). "We have systematically investigated the role of IL-15 in human pan-cancer." (PMID 36467072, 2022). "Higher levels of sIL-15 or IL-15Rα were detected in the plasma of patients with autoimmune diseases or cancers compared to that in healthy donors, raising the concern that high IL-15 levels may be correlated to poor clinical outcomes." (PMID 35806311, 2022). "IL-15 proves to be a promising candidate for cancer immunotherapy due to its functional similarity to IL-2 with several added benefits, including the lack of stimulation on regulatory T cell populations, reduced activation-induced cell death (AICD), and lower toxicity." (PMID 35806311, 2022). "The series of abnormal expressions of lipid metabolism and gluconeogenic signaling pathways that may be induced by the reduction of IL-15 in pan-cancer may lead to the metabolic dysfunction of the body in the development of cancer." (PMID 36467072, 2022). "The protein levels of IL-15 in pan-cancer were assessed by the Human Protein Atlas (HPA)." (PMID 36467072, 2022). "This study highlights the multifaceted role of IL-15 in pan-cancer." (PMID 36467072, 2022). "Altogether, the advantages IL-15 has over IL-2 indicate that it could be a highly effective and safe cytokine for cancer therapy." (PMID 35806311, 2022). "Cytokines such as IL-15 can enhance the anti-cancer activity of NK cells." (PMID 35804808, 2022). "In addition, GPCR(G Protein-Coupled Receptor) ligand binding, infection, phagocytosis, and DNA damage checkpoint pathways were all involved in IL-15 biology function in pan-cancer biological analysis." (PMID 36467072, 2022). "Moreover, GPCR ligand binding, infection, phagocytosis, and DNA damage checkpoints were found to be IL-15 mediated pathways in pan-cancer, which deserved further investigation." (PMID 36467072, 2022). "SOT101 represents a promising IL-15-based immunotherapeutic drug for the treatment of cancer." (PMID 36300122, 2022). "High expression of these genes can improve the prognosis of patients with SKCM and LUAD, which suggests that IL-15 may be able to kill cancer cells by activating the process of ferroptosis/cuproptosis." (PMID 36467072, 2022).
cancer (continued). "Therefore, we used the cBio-portal database to reveal the fact that amplification is the greatest frequency of IL-15 changes in pan-cancer." (PMID 36467072, 2022). "In T-LGLL, excess IL-15 is thought to play a part in the link between inflammation and cancer." (PMID 35747794, 2022). "Besides using IL-15 and its derivatives alone in cancer immunotherapy, IL-15 has also been incorporated into many adoptive cell therapies against cancer, specifically in combination with chimeric antigen receptor (CAR) engineering." (PMID 35806311, 2022). "Moreover, we found that CD226, which has cytolytic activity against cancer cells, was enriched on NK-EVs by IL-15 + IL-21 stimulation." (PMID 34316033, 2022). "However, we also found that mRNA expression levels of IL-15 played a cancer-promoting role in GBM, OSCC, LGG, THYM, LIHC, LAML, PAAD, and GBMLGG." (PMID 36467072, 2022). "In addition, pharmacological target exploration can be performed to search for drugs that can target or synergize IL-15 and contribute to clinical cancer treatment." (PMID 36467072, 2022). "Another type of cancer immunotherapy is active immunotherapy, which involves administration of agents, such as interferons, interleukins (e.g., IL-2, IL15, and IL-12), vaccines, and genetically engineered T cells, to direct the immune system into taking an active role in attacking the cancer cells." (PMID 36297474, 2022). "Recently, IL-15 has emerged as a promising cytokine for the treatment of cancer." (PMID 36467072, 2022). "Our findings may serve as a cornerstone of DC-based immunotherapy with novel multipotent IL-15 mDCs in the field of cancer immunotherapy." (PMID 35413499, 2022). "Next, the mRNA expression of IL-15 in human pan-cancer was further assessed in the TIMER database." (PMID 36467072, 2022). "Similarly, anti-IM9 T cells and CIK cells stimulated with IL-15 mDCs (6 days) displayed higher IFN-γ spot production against IM9 cancer cells compared to the other groups." (PMID 35413499, 2022). "So far, the combination of NIR-PIT with immune checkpoint inhibitors such as anti-PD-1 and anti-CTLA-4 mAbs, or with activation cytokines such as IL-15 have been tested and shown effective in augmenting the efficacy of cancer-cell targeted PIT by enhancing the anti-cancer immune activation." (PMID 36185287, 2022). "However, key differences in production, receptor affinity and secretion confer unique properties to IL-15, and advantages over IL-2 for the treatment of cancer." (PMID 34799399, 2021). "Therefore, a more convenient technique for expressing exogenous IL-15 and IL-15Rα genes in cancer cells is needed." (PMID 34439192, 2021). "ADAM17 blockade in combination with IL-15 may provide a new approach to improve NK cell persistence and function in cancer patients." (PMID 34367174, 2021). "Therefore, many clinical trials are being conducted to establish IL-15 as a vaccine adjuvant and an important biologics for anti-cancer immunotherapy." (PMID 33953717, 2021). "Our contribution to cancer immunotherapy was the discovery of a methodology for expanding the bispecific antibody platform by crosslinking an anti-CD16 single chain variable fragment (scFv) and an scFv recognizing cancer antigens with the cytokine interleukin 15 (IL-15)." (PMID 34439149, 2021). "After infection with a BV, both the IL-15 and IL-15Rα proteins were well-expressed and could dimerize to form the biologically functional IL-15:IL-15Rα complex in either B16F10 or CT26 cancer cells." (PMID 34439192, 2021). "We previously reported α-galactosyl ceramide (α-GC) and its analogs as strong activators of the anti-cancer effects of NKTs, and combining α-GC or its analog with IL-15 may be a promising add-on approach for anti-GD2 immunotherapy in high-risk NBL." (PMID 33668573, 2021). "The use of IL-15/IL-15Rα in CAR therapy might augment cancer therapy through enhancing CAR survival, effector function, and effective localization to target tissues." (PMID 33410096, 2021).